PDC (phosducin)
Diseases named in the same sentence as PDC in open-access papers (continued):
Sharing a sentence is not in itself a finding about the gene and the disease.
cancer (49 papers, 2010 to 2025). A tumor composed of atypical neoplastic, often pleomorphic cells that invade other tissues. "These genes were previously associated with pDC dysfunction in other human cancers that promoted an immunosuppressive TME by acting as negative regulators of type I IFN production via TGF-β and ILT7 (LILRA4) signaling." (PMID 37669110, 2023). "Although not completely understood, pDC tolerance promotion by activating regulatory T cells (Tregs) had been proposed to explain the associated pDC contribution to immune tolerance in different cancers." (PMID 31777600, 2019). "Novel combinatorial immunomodulatory therapies targeting pDC activation can boost innate and adaptive cancer immunity." (PMID 39020402, 2024). "Despite its small size, the role of pDC in cancer cell killing can be crucial because they have the ability to cross-prime naïve CD8+ T cells by transferring antigen to cDC." (PMID 38500875, 2024). "pDC infiltration in the TME has been associated with both favorable and worse prognosis in several cancer types." (PMID 39483484, 2024). "This review summarizes the current knowledge on the pathophysiology of IRs expressed by pDCs, with a particular emphasis on their hijacking in cancer contexts, where pDC functions are generally reduced or abrogated." (PMID 38504978, 2024). "Increasing evidence suggests that abnormal PDC activity is correlated with the malignant progression of cancer and poor clinical prognosis." (PMID 39882072, 2024). "In silico analysis of a pDC signature in pan-cancer TCGA datasets showed that a high pDC content was limited to TDLNs and stage I primary tumors, whereas pDC signature was poor in CM as compared to primary carcinomas." (PMID 39020402, 2024). "Here, we review the many roles of pDCs in cancer and present current advances in developing pDC-based immunotherapeutic approaches for treating cancer." (PMID 36232698, 2022). "A general relationship was seen between PDC and the seven-step Cancer-Immunity Cycle, among which correlations were mainly found in steps 3, 4, and 5 (Table A4)." (PMID 36119477, 2022). "The aim of this study sought to clarify the potential mechanism by which pDC mediated cancer cell proliferation and lymph node metastasis in oral squamous cell carcinoma." (PMID 33854604, 2021). "Here, we revise novel findings obtained from the recent literature as an extension to previously published reviews on the pDC biology, development, trafficking and on their role in cancer." (PMID 32054102, 2020). "In addition, TLRs activate pDC, a DC subgroup, to release vast amounts of type I IFNs (IFNs) to fight cancer." (PMID 40422244, 2025). "Taken together, these studies demonstrate that the presence of different DC subsets in the TME is correlated with cancer prognosis, with cDC1 and LAMP3+ DC mostly associated with a favorable prognosis while the role of other subsets such as pDC remains controversial." (PMID 39483484, 2024). "In the last decade, studies have proposed a relevant role for pDC also in cancer immunity." (PMID 39020402, 2024). "These limitations could explain the wide heterogeneity that has emerged in pDC frequency in the blood and tissues of cancer patients and its correlation with clinical outcome." (PMID 39020402, 2024). "Potentially, not all cancers cause pDC hypofunction or cause it to various degrees, which would explain observations that some pDCs responded to signaling through TLR7/TLR8." (PMID 36768258, 2023). "At present, phosducin and several phosducin-like proteins (PhLPs) are known to be expressed in various tissues, including the brain, liver, pineal, and olfactory epithelium; however, there are few reports on their relationship with human cancers." (PMID 37006287, 2023). "Moreover, pDC, which have been shown to contribute to cancer pathogenesis were also observed to be male‐biased in HNSC, KRIC, STAD, and THCA." (PMID 35229456, 2022).
cancer (continued). "A precise understanding of the regulatory mechanisms that influence pDC functionality can put missing pieces in the puzzle, showing the picture of the interactions between the immune system and cancer, and thus lead to an improvement in current therapeutic approaches." (PMID 30987228, 2019). "Pharmacological targeting of MEK1/2 signaling may constitute an attractive new approach to study mechanisms of modulation of pDC activation in pathophysiological conditions such as chronic viral infections and cancer." (PMID 29535732, 2018). "Overexpression of PDK1 in cancer cells inhibits PDC-catalyzed tricarboxylic acid cycle, resulting in the inability of aerobic oxidation, may cause cancer cells prefer other material as their new energy source or other metabolic pathway to obtain large amounts of energy substances." (PMID 33403023, 2021). "PDK inhibitors have demonstrated promise in activating PDC, shifting metabolism toward OXPHOS, and promoting apoptosis in cancer cells." (PMID 38689087, 2024). "Cancer cells reprogramme their metabolism by inhibiting PKM2 and enhancing PDC activity, which increased anticancer effects in several types of cancer." (PMID 36810109, 2023). "Three clinically significant and highly studied genes were selected as target genes for each cancer type: HERE2, MYBL2, and MMP11 for BRCA and NOTCH2, BRCA1, and PDC for COAD." (PMID 34422018, 2021). "In conclusion, the role of pDCs in cancer immunoediting is still poorly investigated, mainly due to the lack of appropriate model system for stable pDC manipulation." (PMID 32054102, 2020). "However, no direct pDC-virus interaction in cancers has been reported as yet." (PMID 39020402, 2024). "In addition, Cells that migrated or invaded through the transwell chamber were also decreased in the CXCR-4-silenced cells upon pDC-CM treatment (P < 0.01), suggesting that CXCR-4 may play an important role in pDC-mediated cancer cell proliferation, migration and invasion." (PMID 33854604, 2021).
bacterial infection (6 papers, 2012 to 2021). "To investigate the role of pDC in gut mucosal bacterial infection, we first examined pDC recruitment to colons of mice infected with C. rodentium." (PMID 31024525, 2019). "The functional role of pDC in host adaptive immunity to Cpn and other bacterial infections is largely unexplored." (PMID 24386207, 2013). "In this study we sought to address a poorly understood facet of pDC biology; their role in immune responses to bacterial infections." (PMID 23119083, 2012). "Thus, plasmid targeting by PDC is not only expected to offer a novel alternative for resistant bacterial infections but will also aid in blocking the transfer of antibiotic resistance." (PMID 32483454, 2020).
neurodegenerative disease (5 papers, 2012 to 2023). A disorder of the central nervous system characterized by gradual and progressive loss of neural tissue and neurologic function. "MAM, which served as a positive control for NDMA in the present animal study, is etiologically associated with ALS/PDC, a prototypical neurodegenerative disease." (PMID 37441677, 2023). "Our findings that BMAA may affect neuronal differentiation further suggest that some sporadic neurodegenerative diseases, including ALS/PDC, may in fact be the end result of dysregulated developmental or cell differentiation processes." (PMID 36893156, 2023).
infectious disease (2 papers, 2013). A disorder directly resulting from the presence and activity of a microbial, viral, or parasitic agent in humans. "Neonates are highly susceptible to infectious diseases and defective antiviral pDC immune responses have been proposed to contribute to this phenomenon." (PMID 23326320, 2013). "Further studies on pDC mediated mechanisms will provide deeper understanding on the linkage between immunoregulation and development of optimal host immunity against infectious diseases." (PMID 24386207, 2013).
gastrointestinal tumors (1 paper, 2024). "This review examines pDC roles in various GI tumors and their potential as therapeutic targets." (PMID 38927922, 2024).
PDC also shares sentences with these, for which no sentence is quoted: colorectal cancer (3 papers); hematologic malignancies (3); Allergy (2); cognitive deficits (2); eosinophilia (2); immune disorders (2); lactic acidosis (2); acute myeloid leukemia (1); Bladder Cancer (1); chronic hepatitis (1); dementia (1); dyslipidemia (1); endotoxemia (1); erythrocytosis (1); fibrosis (1); gastric cancer (1); glioblastoma (1); Globozoospermia (1); Glucose intolerance (1); granulomatosis with polyangiitis (1); head and neck squamous cell carcinoma (1); hookworm infection (1); Intellectual disability (1); Klebsiella Infections (1); leukemia (1); lung disorder (1); lupus erythematosus (1); Lymphadenopathy (1); myelodysplastic syndrome (1); neurological diseases (1).
A further 10 diseases each share a sentence with PDC in 1 paper.